RN7SL602P (RNA, 7SL, cytoplasmic 602, pseudogene)
Gene: Miscellaneous RNA gene on chromosome 2 (34,809,233 to 34,809,556, reverse strand). Ensembl gene ENSG00000264352.
Homologues: Paralogues in human: RN7SL718P (81% identical), Metazoa_SRP (78% identical), Metazoa_SRP (77% identical), Metazoa_SRP (76% identical), RN7SL440P (76% identical), Metazoa_SRP (75% identical), RN7SL524P (74% identical), Metazoa_SRP (73% identical), Metazoa_SRP (72% identical), RN7SL525P (71% identical), RN7SL121P (71% identical), Metazoa_SRP (70% identical), and 712 more.